VWA1 (von Willebrand factor A domain containing 1)
Description:
Promotes matrix assembly (By similarity). Involved in the organization of skeletal muscles and in the formation of neuromuscular junctions (Probable).
Synonyms: FLJ22215; VWA-1; WARP; HMNMYO; HMNR7
Tractability: Antibody: UniProt places it where antibodies can reach, with medium confidence; UniProt predicts a signal peptide or a membrane-spanning region; its Gene Ontology location is reachable by antibodies, with medium confidence.
Gene: Protein-coding gene on chromosome 1 (1,434,861 to 1,442,882, forward strand). Ensembl gene ENSG00000179403.
Subcellular location: Secreted, extracellular space, extracellular matrix, basement membrane
Pathways (Reactome):
Metabolism of proteins: Post-translational protein phosphorylation; Regulation of Insulin-like Growth Factor (IGF) transport and uptake by Insulin-like Growth Factor Binding Proteins (IGFBPs)
Gene Ontology:
Molecular function: extracellular matrix structural constituent; identical protein binding; microfibril binding; protein homodimerization activity
Cellular component: extracellular exosome; extracellular matrix; extracellular region; endoplasmic reticulum lumen; basement membrane; interstitial matrix
Genetic constraint (gnomAD): Loss-of-function variants: 12 observed, 12.79 expected, observed/expected ratio (o/e) 0.94, 90% interval 0.6 to 1.51. The synonymous counts are far from expectation, so gnomAD's model fits this gene poorly and the ratio says little. Missense variants: 800 observed, 548.02 expected, observed/expected ratio (o/e) 1.46, 90% interval 1.38 to 1.55. Synonymous variants: 368 observed, 253.07 expected, observed/expected ratio (o/e) 1.45, 90% interval 1.34 to 1.59.
Homologues: Orthologues: chimpanzee VWA1 (99% identical), pig VWA1 (82% identical), dog VWA1 (80% identical), guinea pig VWA1 (77% identical), mouse Vwa1 (73% identical), rat Vwa1 (73% identical), macaque VWA1 (72% identical), tropical clawed frog vwa1 (46% identical), zebrafish vwa1 (33% identical). Paralogues in human: COL14A1 (23% identical), COL12A1 (22% identical), COL6A3 (20% identical), COL6A5 (18% identical), COL6A6 (17% identical), MATN2 (17% identical), VWA2 (16% identical), MATN4 (15% identical), MATN1 (14% identical), MATN3 (14% identical), COCH (11% identical), VIT (11% identical).
Diseases named in the same sentence as VWA1 in open-access papers:
VWA1 is named in the same sentence as 26 diseases in open-access papers, as found by Europe PMC text mining. Sharing a sentence is not in itself a finding about the gene and the disease. The quoted sentences say what the papers report.
axonal motor neuropathy (2 papers, 2021 to 2024). "The recent identification of truncating biallelic variants in VWA1 has unveiled a novel hereditary neurological condition with a phenotype that continues to expand, encompassing non–length-dependent axonal motor neuropathy with early involvement of proximal limbs and upper extremities." (PMID 39502942, 2024).
myocardial infarction (2 papers, 2015 to 2025). Gross necrosis of the myocardium, as a result of interruption of the blood supply to the area, as in coronary thrombosis. "Higher vWA1 expression has been associated with cardiac remodeling, and promoting repair, instead of fibrosis, following myocardial infarction injury." (PMID 40354360, 2025).
neuropathies (2 papers, 2021 to 2025). "Indeed, recentpapers highlight the embryonic origin of many neuropathies and this may potentially explainthe involvement of VWA1 in the CNS malformations associated with 1p36deletion syndrome." (PMID 33559681, 2021).
hereditary spastic paraplegia (1 paper, 2024). Hereditary spastic paraplegias (HSP) comprise a genetically and clinically heterogeneous group of neurodegenerative disorders characterized by progressive spasticity and hyperreflexia of the lower limbs. "Therefore, VWA1 should be included in multiple gene panels covering hereditary neuropathies, muscle dystrophies, hereditary spastic paraplegia and SMA to reduce diagnostic delay and identify a large number of undiagnosed individuals." (PMID 39502942, 2024).
lung carcinoma (1 paper, 2023). "Stratified analysis by smoking status highlighted two proteins, IGFBP-1 and VWA1, that had stronger lung cancer risk associations in current vs former smokers (phet < 0.05)." (PMID 37264016, 2023).
muscular dystrophies (1 paper, 2024). "Importantly, VWA1-related pathology may mimic various neuromuscular conditions, advocating for its inclusion in diverse gene panels spanning hereditary neuropathies to muscular dystrophies." (PMID 39502942, 2024).
Obesity (1 paper, 2021). Accumulation of substantial excess body fat. "Four genes were identified to be significantly affected by aging, obesity, and exercise (Serpinh1, Vwa1, Mest, and Fhl3)." (PMID 33661096, 2021). "Two genes, Serpinh1 and Vwa1, were found to be significantly increased by both aging and obesity and decreased by exercise, suggesting that they could act as common mediators of EC dysfunction." (PMID 33661096, 2021).
schizophrenia (1 paper, 2023). A major psychotic disorder characterized by abnormalities in the perception or expression of reality. "HsVWA5/BCSC-1, which sequence alignments suggest is orthologous to Vwa1, is tumor suppressing and schizophrenia-associated as summarized above." (PMID 37779900, 2023).
scleroderma (1 paper, 2023). Scleroderma is a rare autoimmune connective tissue disorder characterized by abnormal hardening of the skin and, sometimes, other organs. "Von Willebrand factor (VWF) and Von Willebrand factor A domain containing 1 (VWA1) are responsible for platelet adhesion and clot formation and were more highly expressed in scleroderma compared to control, indicating possible causes for microvascular damage." (PMID 37443817, 2023).
tumor (9 papers, 2020 to 2025). "Tumor endothelial cells were mainly represented by clusters 2 and 4, and showed high expression of angiogenesis markers such as VWA1 and HSPG2, as well as INSR, encoding an endothelial marker protein and possible therapeutic target (arrowheads)." (PMID 34663877, 2021). "A further cluster of immature endothelial cells (Endo Imm), defined by expression of PLVAP, VWA1, and CA4, was identified and has been implicated in poor tumor prognosis." (PMID 40161579, 2025). "We obtained five cell subpopulations, including four clusters (C0, C1, C2, C4) of tumor endothelial cells (PLVAP, VWA1, HSPG2, and INSR) and lymphatic endothelial cells (C3) (PDPN, CCL21)." (PMID 37715019, 2023). "The VIT-vWFA domain arrangement of Vwa1 is characteristic of a broad protein family that includes extracellular ITIH heavy chains, a specific intracellular poly ADP-ribose polymerase (PARP4), and the intracellular tumor suppressing VWA5A/BCSC-1." (PMID 37779900, 2023). "While C2 (VWA1+) and C3 (IL13RA2+) were nearly derived from tumor tissues." (PMID 36483553, 2022).
VWA1 also shares sentences with these, for which no sentence is quoted: malaria (4 papers); infection (3); breast cancer (2); cancer (2); 1p36deletion syndrome (1); dementia (1); infarction (1); ischemic heart disease (1); liver disease (1); mandibulofacial dysostosis (1); microtia (1); myopathy (1); neurogenic muscular atrophy (1); neurological diseases (1); neuromuscular disease (1); type 1 diabetes mellitus (1).